LGR6 (leucine rich repeat containing G protein-coupled receptor 6)
Diseases named in the same sentence as LGR6 in open-access papers (continued):
Sharing a sentence is not in itself a finding about the gene and the disease.
cancer (25 papers, 2012 to 2025). A tumor composed of atypical neoplastic, often pleomorphic cells that invade other tissues. "The ICBatlas analysis revealed the conserved bidirectional pattern (protective MAOB/SERPINA1 vs. risk-enhancing IGFBP2/LGR6) of the four-gene signature as a pan-cancer theoretical framework for risk stratification." (PMID 40821817, 2025). "Lgr6 is a G protein-coupled receptor (GPCR) that has been implicated in cancer progression and in activation of Wnt signaling." (PMID 32309216, 2020). "All these analyses confirmed an existing correlation between the lack of the cellular differentiation, the increased expression of Wnt signalling components and p38α deficiency in LGR6+ cancer cells." (PMID 31236545, 2019). "Two of the LGR6(+) patients have died from their cancer and the third patient from other causes." (PMID 38715790, 2024). "In the present study the molecular technique qRT-PCR was used to analyze extracts from as much as half the LN thereby strongly increasing the probability of detecting LGR6 mRNA from cancer stem cells." (PMID 38715790, 2024). "High testosterone increased the expression of WNT4 and LGR6, which have both been described as cancer stem cell (CSC) markers in both human tissues and immortalized cell lines." (PMID 37046723, 2023). "The number of Lgr6+ cells in the control organoids was higher than that in the cancer organoids, while the number of Hopx+ cells in the cancer organoids was higher than that in the control organoids." (PMID 34785704, 2021). "In both control and cancer organoids, the expression of Hopx and the suprabasal keratinocyte markers Krt13, Krt4, and Krt6a increased with pseudotime while Lgr6-expressing cells were enriched in undifferentiated cells." (PMID 34785704, 2021). "LGR6 binds to RSPO ligands to activate the Wnt/β-catenin signaling pathway to promote cancer progression." (PMID 33429364, 2021). "The progenitor marker Lgr6 was expressed in the stem-like cell clusters of both control and cancer organoids, whereas Hopx was mostly expressed in clusters with low StemID values." (PMID 34785704, 2021). "We explored the relationship between the expression of LGR6 in cancer tissues from 102 ESCC patients and their clinicopathological features." (PMID 31917882, 2020). "Similar to normal stem cells, LGR6+ cancer cells show self-renewal and differentiation capacities, alongside with a higher oncogenic potential." (PMID 31236545, 2019). "Disruption in the balance of this network was observed in LGR6+ cancer cells, supporting the SC-like properties of these lung tumour cells." (PMID 31236545, 2019). "Similar to the controversial roles of LGR6 in different types of cancer, LGR proteins, including LGR4–6, have been demonstrated to play an opposite, even paradoxical, role in regulating Wnt/β-catenin signaling." (PMID 31193124, 2019). "We also sorted Lgr6+ cancer stem cells from K14Cre;TRF2f/f;Terc-/- and control SCC by flow cytometry." (PMID 29113290, 2017). "In our present study, DMBA-induced CD34+ and Lgr6+ cancer stem cells were characterized by extensive telomere shortening despite ALT activation." (PMID 29113290, 2017). "Despite their significant depletion, CD34+ and Lgr6+ cancer stem cells were tumorigenic following transplantation." (PMID 29113290, 2017). "Both CD34+ and Lgr6+ cancer stem cell populations from K14Cre;TRF2f/f;Terc-/- SCCs were tumorigenic in our transplantation experiments." (PMID 29113290, 2017). "These integrin αv expressing cells represented a distinct population from other cancer stem cell populations, including significantly reduced CD34 and Lgr6 expression and failure to give rise to these known cancer stem cell populations." (PMID 29113290, 2017). "Statistically significant associations, corrected for multiple testing, were observed for the transcripts TBX21 and TGFBR3, which are mediators of the immune system, and LGR6 and STX16 that have been repeatedly associated with cancer progression." (PMID 24194869, 2013).
cancer (continued). "To evaluate the pan-cancer robustness of our 4-gene signature (MAOB, IGFBP2, SERPINA1 and LGR6), we leveraged the ICBatlas database—comprising 93,000+ patients across 18 cancer types (including 12 cancers with multi-omics profiling) and 30 immune checkpoint inhibitor (ICI) treatment cohorts." (PMID 40821817, 2025). "Thus, Lgr6 has been identified as a promising therapeutic target for cancer and other diseases, influencing their onset, progression, and treatment." (PMID 41938713, 2025). "Several groups have studied the prognostic value of LGR6 in cancer." (PMID 38715790, 2024). "Last, downregulation of LGR6 reduced cancer stemness as determined by functional in vitro assays." (PMID 37770230, 2023). "For these studies, we chose to focus on two of the most significantly upregulated and novel ligand–receptor pairs: SAA1‐FPR1, because FPR1 expression increased with grade, and RSPO3‐LGR6, because LGR6 has also been noted to be involved in various types of cancers." (PMID 35619544, 2022). "LGR6 is also related to the initiation and progression of some malignant tumors." (PMID 34489551, 2021). "Interestingly, the G protein-coupled receptor Lgr6 is an epithelial stem cell marker that has been shown to promote Wnt receptor signaling and drive progression in multiple cancer subtypes." (PMID 32309216, 2020). "However, further studies should be performed to confirm the suggested potential role of Sox9 and Lgr6, both at the protein and mRNA level, as cancer markers of malignancy." (PMID 32397255, 2020). "Leucine‐rich repeat–coupled receptor 6 (LGR6) is a marker of the skin, nails, and other types of adult tissue stem cells and has been widely found to be related to the development and progression of a variety of cancer types." (PMID 31917882, 2020). "We demonstrated Lgr6+ cancer stem cells in these tumors by immunofluorescence microscopy." (PMID 29113290, 2017). "Finally, we identified cell surface markers for cardiac progenitors, such as the Leucine-rich repeat-containing G-protein coupled receptor 4 (LGR4), belonging to the same subfamily of LGR5, and LGR6, established tissue/cancer stem cells markers." (PMID 26783251, 2016). "Therefore, LGR6 functions differently in different cancers or individuals." (PMID 31917882, 2020). "Thus, suppression of LGR6 function may be important for cancer cells to maintain the right level of Wnt/β-catenin signaling." (PMID 22615920, 2012). "Therefore, it is important to determine if LGR6 interacts with the different RSPOS to regulate Wnt/β-catenin signaling and whether the cancer mutations affect LGR6-mediated signaling." (PMID 22615920, 2012). "In this study we showed that addition of exogenous testosterone reduced apoptotic signals, such as p21, while increasing cancer stem cell markers WNT4 and LGR6." (PMID 37046723, 2023). "We conclude that LGR6 mRNA analysis of LNs from CC patients can serve as an important complement to CEA- or CXCL16 mRNA analysis detecting cancer stem cells which express very low levels or no mRNA for these two markers." (PMID 38715790, 2024). "Second, comparison of LGR6+ with LGR6- cells after flowcytometric cell sorting might be another elegant way to explore the roles of LGR6 in WNT signaling, EMT, and cancer stemness." (PMID 37770230, 2023). "Our data demonstrated that CD34+ and Lgr6+ cancer stem cells activate the ALT pathway in the absence of TRF2 expression and telomerase activity." (PMID 29113290, 2017). "After 110 months no LGR6(-) patient had died from cancer (Δ = 23 months at 5 years, p<0.001)." (PMID 38715790, 2024). "Cluster 2 contains instead receptor-ligand axes that are more frequently concordantly downregulated in cancer subtypes, although several of these might still be concordantly upregulated in specific subtypes (e.g., CXCR2, EDNRB, FFPR2, or LGR6, GALR2, and UTS2R)." (PMID 38723607, 2024).
cardiovascular diseases (2 papers, 2025 to 2026). "Leucine‐rich repeat‐containing G protein‐coupled receptor 6 (Lgr6) has emerged as a significant player in cardiovascular diseases." (PMID 40211903, 2025).
LGR6 also shares sentences with these, for which no sentence is quoted: acne (3 papers); adenocarcinoma (1); adrenal tumor (1); chronic lung disease (1); clear cell adenocarcinoma (1); colon adenocarcinoma (1); COVID-19 (1); endometrial cancer (1); endometrioid adenocarcinoma (1); epilepsy (1); glioblastoma (1); gynecological cancers (1); hearing loss (1); heart failure (1); hypertrophy (1); infectious colitis (1); Infertility (1); Insulin resistance (1); ischemia (1); kidney damage (1); lung diseases (1); medulloblastoma (1); mucinous adenocarcinoma (1); ovarian serous cystadenocarcinoma (1); ovarian tumors (1); pancreatic adenocarcinoma (1); pancreatic cancer (1); pilomatricomas (1); pituitary adenoma (1); postmenopausal osteoporosis (1).
A further 5 diseases each share a sentence with LGR6 in 1 paper.